MTFR1L (mitochondrial fission regulator 1 like)
Description:
Mitochondrial protein required for adaptation of mitochondrial dynamics to metabolic changes. Regulates mitochondrial morphology at steady state and mediates AMPK-dependent stress-induced mitochondrial fragmentation via the control of OPA1 levels.
Synonyms: FAM54B; HYST1888; MSTP116; MST116
Tractability: Antibody: UniProt places it where antibodies can reach, with high confidence. PROTAC: ubiquitination databases record sites on it; its protein half-life has been measured.
Gene: Protein-coding gene on chromosome 1 (25,818,640 to 25,832,947, forward strand). Ensembl gene ENSG00000117640.
Subcellular location: Mitochondrion outer membrane
Subcellular location (Human Protein Atlas): Mitochondria; Cell Junctions
Gene Ontology:
Molecular function: protein binding
Biological process: aerobic respiration; mitochondrial fission
Cellular component: mitochondrial outer membrane; mitochondrion
Genetic constraint (gnomAD): Loss-of-function variants: 10 observed, 29.18 expected, observed/expected ratio (o/e) 0.34, 90% interval 0.21 to 0.58. The upper end of that interval is the gene's LOEUF score, 0.58, which puts it in group 2 of 6, group 1 being the genes least tolerant of losing a copy. Missense variants: 315 observed, 380.09 expected, observed/expected ratio (o/e) 0.83, 90% interval 0.75 to 0.91. Synonymous variants: 151 observed, 146.11 expected, observed/expected ratio (o/e) 1.03, 90% interval 0.9 to 1.18.
Homologues: Orthologues: dog MTFR1L (99% identical), macaque MTFR1L (97% identical), pig MTFR1L (97% identical), chimpanzee MTFR1L (96% identical), rabbit MTFR1L (96% identical), guinea pig MTFR1L (95% identical), mouse Mtfr1l (95% identical), rat Mtfr1l (92% identical), zebrafish mtfr1l (57% identical), tropical clawed frog mtfr1l (56% identical). Paralogues in human: MTFR2 (30% identical), MTFR1 (26% identical).
Diseases named in the same sentence as MTFR1L in open-access papers:
MTFR1L is named in the same sentence as 5 diseases in open-access papers, as found by Europe PMC text mining. Sharing a sentence is not in itself a finding about the gene and the disease. The quoted sentences say what the papers report.
breast carcinoma (1 paper, 2022). "However, we found underexpression of EEF2 and GLRX2 proteins involved in ROS; MTX2 in MMO; USP30 in MIT; TSPO in MIT and PPM processes; BAX in FUS; and MTFR1L and MIEF1 in FIS compared to luminal A and basal-like breast cancer tumors." (PMID 35327574, 2022).
metastatic tumor (1 paper, 2020). "In addition, the expression of NFE2L1 and MTFR1L in metastatic tumor samples is lower than that in primary tumor samples." (PMID 32316228, 2020).
mitochondrial disease (1 paper, 2022). "Thus, increasing OPA1 levels by targeting or inhibiting MTFR1L may represent a potential unexplored therapeutic target for mitochondrial diseases." (PMID 36367943, 2022).
MTFR1L also shares sentences with these, for which no sentence is quoted: tumor (2 papers); glioblastoma (1).